GZMB (granzyme B)
Diseases named in the same sentence as GZMB in open-access papers (continued):
Sharing a sentence is not in itself a finding about the gene and the disease.
tumor (continued). "By targeting the G2/M checkpoint, these interventions may increase the susceptibility of tumor cells to the cytotoxic effects of granzyme B, potentially overcoming resistance mechanisms and enabling more efficient immune elimination of tumor cells." (PMID 40766321, 2025). "However, an increased proportion of CD8+ lymphocytes expressing Granzyme B within the tumour epithelium was associated with improved survival on adjusted analysis (HR 0.51, 0.27-0.96)." (PMID 41487587, 2025). "Additionally, ASMase deficiency in CD8+ T cells led to reduced granzyme B production, impaired cytotoxicity, and diminished tumor size/burden." (PMID 40597360, 2025). "Given that granzyme B is a key effector molecule in the antitumor response of cytotoxic T lymphocytes and natural killer (NK) cells, this finding highlights a potential mechanism underlying the observed tumor suppression." (PMID 40429884, 2025). "In parallel, supraphysiological pulses re-programme tumour-associated macrophages toward an iNOS-rich M1 phenotype, amplify granzyme-B output from CD8+ T cells and down-tune PD-L1 expression on malignant and myeloid cells, thereby widening the therapeutic window of immune-checkpoint blockade." (PMID 40791587, 2025). "Immune marker analyses of Ing4-deleted tumors revealed a significant increase in tumor-associated macrophages (Gr-1loCD11b+F4/80+) and a decrease in granzyme B-positive (GzmB+) CD4+ T cells, indicating a suppressive and/or less tumoricidal immune microenvironment." (PMID 38968186, 2024). "In addition, we discovered that IL-23 and PD-1 mAb had a synergistic effect in improving anti-tumor immune response, which was associated with increased levels of cytotoxic molecules such as Granzyme B and IL-2." (PMID 38902343, 2024). "Despite the expression of these exhaustion markers, antigen-specific intratumoral CD8 T cells were able to secrete IFNγ, TNFα, and Granzyme B upon ex vivo restimulation, showing that they maintained their functionality, which was associated with tumor regression." (PMID 38893156, 2024). "In addition to tumor‐associated biomarkers, granzyme B is an essential serine protease involved in cytotoxic T cells killing." (PMID 39175888, 2024). "Similarly, ELISA results showed increased granzyme B and perforin in the tumor-grinding fluid of TREM2-deficient mice, which were further enhanced by GB1107 treatment." (PMID 39135069, 2024). "Interestingly, combination therapy reshaped the tumor microenvironment via cytokines associated with natural killer cells, supported by eradication of immune checkpoint galectin-1 and elevated granzyme B levels." (PMID 38160212, 2024). "Subsequently, the tumor organoids were treated with anti‐PD‐1 and anti‐PD‐L1 agents, and the mRNA expression levels of crucial markers (granzyme B, perforin 1, and IFN‐γ) associated with tumor‐infiltrating T cell proliferation and activation were meticulously assessed." (PMID 38815251, 2024). "However, the present study reveals that CAP treatment enhances the expression of PD-1 and PD-L1 in T cells and tumor cells, respectively, but reduces the expression of T cell cytokines (IFNγ, GZMB, and IL-2) that are associated with CTL functions and activity." (PMID 37189453, 2023). "We could demonstrate that upregulation of granzyme B in the tumor periphery was associated with disease progression resulting in a significantly worse CSS of ccRCC patients." (PMID 37894418, 2023). "We have proven that CAR-Exos may target and kill tumor cells directly via producing granzyme B and perforin, resulting in the release of tumor-associated antigens and activation of the immune response." (PMID 37308954, 2023). "Thus, lowered neutrophil counts and concomitants reduction in MMP-9-positive tumor tissue cells together with increased Granzyme B-positive tumor-associated cells, reflect the anti-cancer mechanisms of AAT augmentation therapy." (PMID 37532996, 2023).
tumor (continued). "Furthermore, in NSCLC cells, autophagy inhibition with rocaglamide (a novel natural molecule capable of targeting ULK1 translation) restored tumor intracellular granzyme B, and thus susceptibility to NK cell killing." (PMID 38071322, 2023). "Collectively, our results and previous reports suggested that ELFN1-AS1 in CRC cells might directly affect JNK signaling in NK cells to suppress the surface expression of NKG2D and GZMB resulting in a marked deficiency in tumor cytotoxicity." (PMID 37147528, 2023). "In addition, natural killer cells induce the pyroptosis of GSDME-expressing tumour cells, and the underlying mechanisms are mediated by secreting granzyme B, which directly cleaves GSDME or activates caspase-3 to indirectly cleave GSDME." (PMID 35896522, 2022). "In addition, granzyme B from killer T cells directly cleaves gasdermin E and causes pyroptosis in tumor cells." (PMID 36038533, 2022). "In comparing the occurrence and development of normal tissues and tumor tissues, we found that the expression levels of genes encoding activation and cytotoxic molecules, such as GZMB, GZMH, GZMK, GZMA, and NKG7, increased significantly and had strong correlations with signs of exhaustion." (PMID 35634956, 2022). "In contrast, GZMB, a low-risk gene for tumor suppression, was positively associated with protective immune-related cells such as CD8+ T cells, M1 macrophages, and negatively associated with tumor progression immune-related cells such as activated dendritic cells." (PMID 35574296, 2022). "This, in addition to GzmB produced by mast cells, prompts the speculation that the production and secretion of GzmB causes extracellular remodeling, which aids tumor migration and metastasis." (PMID 35326588, 2022). "Apart from the direct tumoricidal effects of Doxil, it also displayed various immunomodulatory properties, such as the induction of ICD, the depletion of MDSC, and enhanced susceptibility of cancer cells to CTL-released granzyme B, all contributing to an elevated anti-tumor immune response." (PMID 35693776, 2022). "Additionally, continual treatment of BRAFi- or BRAFi/MEKi-resistant tumors with BRAFi renders tumor cells more susceptible to killing by cytotoxic lymphocytes through transiently enhancing uptake of the T cell cytotoxic molecule, granzyme B." (PMID 34025662, 2021). "The cytokines IFN-γ, TNF-α, granzyme B and the membrane protein CD107a are phenotypic markers whose combinatorial expression by lymphocytes is associated with cytotoxic function in multiple contexts, including clinically effective anti-tumor responses." (PMID 34584159, 2021). "The conclusions and prospect may facilitate better interpretations of the clinical significance of granzyme B, guiding the rational development of therapeutic regimen and diagnostic probes for anti-tumor purposes." (PMID 33868318, 2021). "In contrast, METTL3-deficient NK cells from tumor-bearing mice exhibited remarkably decreased protein expression of CD107a, GzmB and IFN-γ than METTL3-sufficient NK cells, indicating METTL3 deficiency-mediated inhibition of cytotoxicity and cytokine production of NK cells in the TME." (PMID 34535671, 2021). "Among the strategies that tumor cells employ to survive the adversities caused by effector lymphocytes, the one for overcoming GrB-mediated apoptosis is unique and convergent on SERPINB9, the well-defined granzyme B inhibitor that protects its host from being killed by this cytotoxic molecule." (PMID 33868318, 2021). "Additionally, BATF-deficient tumor-reactive CD8+ T cells had significantly lower expression of granzyme B, a cytolytic molecule produced by effector lymphocytes." (PMID 33809259, 2021). "Finally, greater numbers of NK cells with associated granzyme B infiltrated the tumor bed in Mmp2-KO tumors." (PMID 34032639, 2021).
tumor (continued). "In the current study, we found the disease progression caused by GM-CSF in T-cell lymphoma was associated with the decreases of tumor-infiltrating T cells and granzyme B release, which could be restored with PD-1 therapy." (PMID 34051805, 2021). "Once internalized in target cells, exosome-associated Granzyme B may induce caspase 3–7 activation resulting in tumor cell apoptosis and death." (PMID 32178479, 2020). "In addition, an increased amount of IFN-γ+ tumor-specific T cells and granzyme B were displayed, which was associated with a significant delay in tumor progression." (PMID 32674255, 2020). "In LLC-bearing mouse model, the combination of MMC and PD-L1 antibody was found to be more effective in retarding tumor growth and prolonging overall survival than either single treatment alone, which was associated with increased lymphocyte infiltration and granzyme B release." (PMID 32855386, 2020). "Additionally, MCPyV TAg-specific cells gated on CD3+CD4+TNFα+ cells were polyfunctional for IL-2 and the Th1 effector molecules granzyme B, IFNγ, and TNFα, a feature associated with immune-mediated tumor clearance." (PMID 33362774, 2020). "In addition to the overall change in T-cell populations, the number of CD8+ T-cells expressing Granzyme B (GzmB+) and PD-1 increased over the course of tumor growth, while the number of Tregs, associated with immune suppression significantly decreased." (PMID 31779705, 2019). "Moreover, there is ample evidence of perforin-independent functions of GzmB that can be linked to tumor metastasis." (PMID 31212684, 2019). "To study the mechanisms underlying the enhanced tumor outgrowth, we first studied whether GzmB enhances the migratory capacity of tumor cells by degradation of the ECM." (PMID 31212684, 2019). "Tumor-associated neutrophils from rats or mice could expressed GZMB, independently of LipA treatment." (PMID 29983866, 2018). "The analysis of the tumor-infiltrating cells indicated that CD49a+ CD49b+ cNK subset was only found in RBPJ-deficient animals that were more efficient than the conventional cNK subset in secreting GzmB and TNFa." (PMID 29930552, 2018). "Otherwise, chemotherapy can induce IL-2 and IFNγ secretion to trigger immunogenic cell death, and increase the permeability of tumor cells to granzyme B, thereby rendering them to be susceptible to CTL-mediated lysis even if they do not express the antigen recognized by CTLs." (PMID 26459255, 2016). "Moreover, the expression of granzyme B and proliferation-associated marker Ki-67 in tumor-infiltrating CD3+CD56+ NKT-like cells were also decreased." (PMID 27409423, 2016). "Allotransfer was demonstrated to mediate the expansion of CTLs, resulting in higher levels of granzyme B. In addition, the expansion of Tregs, which is associated with tumor progression, was significantly suppressed at the later stages following allogeneic transplantation." (PMID 25009582, 2014). "Mechanistic studies revealed that dual anti-OX40/IL-2c therapy significantly increased the proliferation (Ki-67) and differentiation (granzyme B) of anergic tumor-associated Ag-specific CD8 T cells, while reducing their expression of the senescence-associated molecule KLRG1." (PMID 22496812, 2012). "Tumor-controlling potential of MAIT cells is generally associated with the increased tumor-infiltrating MAIT cells exhibiting a Th1 phenotype that secreted granzyme B and, to a lesser extent, perforin, suggesting a protective antitumor role in colon adenocarcinomas." (PMID 40746558, 2025). "Although GZMB is a serine protease produced by cytotoxic lymphocytes and natural killer cells, typically associated with target cell apoptosis and considered a marker of anti-tumor immunity, its elevated expression in IBC correlated with immunosuppressive cell activation and an adverse prognosis." (PMID 41567210, 2025). "Consequently, they proposed that tumor-associated GZMB promotes cancer invasion and EMT." (PMID 41567188, 2025).
tumor (continued). "Interestingly, the increase in kynurenine uptake, proliferation, and GzmB expression after PD-1 blockade was associated with a reduction in tumor size in lean and obese mice, but levels of kynurenine uptake and GzmB exceeded those of control mice at the same tumor size." (PMID 35103755, 2022). "GZMB encodes for the similar named protease granzyme B, that is released by effector T cells to induce apoptosis of tumor cells, and the c.128C > A SNP is hypothesized to define an isoform of granzyme B that is incapable of apoptosis in tumor cell lines." (PMID 33803602, 2021). "CD16+ CD8+ T cells exhibit natural killer (NK)-like and are terminally differential memory effector T phenotype with high levels of granzyme B and perforin, indicating this small group of effector CD8+ T cells may exhibit anti-tumor potential since granzyme B and perforin causes tumor apoptosis." (PMID 34685495, 2021). "Granzyme B (GrB) is a serine protease traditionally known for its perforin-dependent pro-apoptotic function underlying the capability of cytotoxic immune cells, as cytotoxic T lymphocytes (CTLs) and natural killer (NK) cells, to kill tumor and virus-infected target cells." (PMID 33262766, 2020). "In addition, Th9 cells can directly cause tumor cell death through granzyme B on their surface." (PMID 32228589, 2020). "Besides, tumor-associated mast cells could modulate cytotoxic function of T cells as perforin and granzyme B production from the T cells cocultured with PD-L1-expressing mast cells decreased significantly." (PMID 30808413, 2019). "Thus, mice deficient in gzmA, gzmB cluster, or both are more susceptible to infection with herpesvirus, particularly cytomegalovirus, and mousepox, ectromelia virus, but their role in NK cell-mediated tumour rejection has been controversial." (PMID 21853094, 2011). "CD8+ T cells are crucial mediators of anti-tumor immunity, eliminating cancer cells by secreting granzyme B and triggering apoptosis." (PMID 41592073, 2026). "The released magnesium ions and TEPP‐46 further enhanced T cell activation and mitochondrial function, promoting ATP and granzyme (GZMB) production, thereby effectively eliminating residual tumor cells." (PMID 41178512, 2026). "In a clinically relevant B16-OVA melanoma model, our spleen-targeted LNPs elicited robust antitumor immunity, characterized by retarded tumor growth, reduced tumor burden, and enhanced infiltration of cytotoxic T cells expressing granzyme B and IFN-γ." (PMID 41541271, 2026). "Lytic IFNγ is present in tumor-infiltrating CTLs and is cosecreted with granzyme B (GzmB) in both soluble form and as part of supramolecular attack particles (SMAPs)." (PMID 41781697, 2026). "The expression of T cell activation markers (CD25 and CD69), as well as anti-tumor cytokines (GZMB, IFNγ, and PRF1), was significantly suppressed when incubated with the supernatants of NAC-pre-treated neutrophils." (PMID 41516400, 2026). "Our results revealed elevated granzyme B expression in the lymph node CD8+ T-cells from dual IPI-549/PD-L1-treated tumor-bearing mice Compared to PD-L1 and IPI-549 single-treatment groups." (PMID 41431358, 2026). "Further evidence of enhanced cytotoxicity in IPI-549/PD-L1 treated tumor-bearing mice is demonstrated by the increased production of the cytotoxic enzyme granzyme B in CD8+ T-cells of tumor draining lymph nodes." (PMID 41431358, 2026). "This remodelling promoted CD8+ T cell infiltration and cytotoxic function, as evidenced by increased Granzyme B secretion, effectively transforming immune “cold” tumours into “hot” tumours." (PMID 41481002, 2026).
tumor (continued). "This combinatorial strategy also reshaped the tumor immune landscape by increasing activated NK cells, elevating Granzyme B expression in CD4+ T cells, and decreasing immunosuppressive M-MDSCs expressing CD39, CD38, and CD73." (PMID 41668741, 2026). "Exploratory analysis suggested higher baseline CD8+ T cells and lower tumor Ki-67 was associated with response, whereas low baseline CD8+ T cell and Granzyme B infiltration correlated with higher exponential tumor growth rate." (PMID 41844546, 2026). "This combination enhanced cytotoxic T cell infiltration into the tumor core, increased granzyme B expression, and induced widespread tumor cell apoptosis, consistent with improved vascular normalization." (PMID 41683994, 2026). "Cytokine bead arrays quantified IFN-γ, granzyme A, and granzyme B levels to assess anti-tumor immune activation." (PMID 41800236, 2026). "Functional assays indicate that IFNγ contributes to CTL-mediated tumor cell death by acting in concert with granzyme B and perforin to increase cytotoxicity and promote apoptosis via the IFNγ-STAT1-caspase-3 pathway." (PMID 41781697, 2026). "Surgical margins underwent multi-modal assessment, including histopathology (tertiary lymphoid structures), tumor burden (Pan-CK, Ki-67), molecular profiling (driver mutations, PD-L1 RNA), and immune contexture (CD8+/FoxP3+ ratio, Granzyme B)." (PMID 41727460, 2026). "To further assess the local immune activation within the tumor microenvironment, we performed immunohistochemical staining for granzyme B and interferon-gamma (IFN-γ)." (PMID 41541271, 2026). "Mice with a genetic deletion of PI3Kγ injected with an HNSCC cell line were found to have increased CD8+ T-cell infiltration and granzyme B production in the tumor microenvironment." (PMID 41431358, 2026). "MUT tumors showed high tumor mutation burdens with APOBEC-associated kataegis and cytolytic/immune-activation programs with M1 macrophage including upregulation of GZMA, GZMB, and large-scale transition." (PMID 41991965, 2026). "IHC showed that GZMB-positive areas occupied 64.3% ± 7.1% of the tumor in the combination group (versus 7.2% ± 1.5% in PBS, ​​*P < 0.001), and IFN-γ expression increased 5.8-fold (*​P < 0.01)." (PMID 41522604, 2026). "Tc22 cells, another subset within the CD8+ T cell population, secrete granzyme B and possess substantial cytotoxic activity, highlighting their distinct anti-tumor potential in adoptive cell immunotherapy." (PMID 40458394, 2025). "This pattern identifies pDCs as a predominant cellular source of GZMB within the IBC tumor microenvironment." (PMID 41567210, 2025). "In one study, over 50% of resected CCAs showed CD8+ tumor‐infiltrating lymphocytes (TILs), with approximately 30% expressing granzyme B, indicating functional activity." (PMID 41143064, 2025). "Expression of CD95 and granzyme B is associated with CD8+ T cell activation and tumor cell killing, whereas activation of the programmed cell death ligand 1 (PD-L1)/PD-1 pathway leads to inhibition of T cell activation." (PMID 40299757, 2025). "Conversely, MCs can also exhibit anti-tumor properties by releasing TNF-α, granzyme B, and IL-17, which enhance anti-tumor immunity." (PMID 40272538, 2025). "CAR-NK cells offer the ability to directly lyse tumor cells via granzyme B, perforin, and death receptor pathways, while also recruiting other immune effectors through cytokine secretion." (PMID 40723278, 2025). "To confirm the exhausted status of CD8+ T cells following co-culture with MC38 tumor cells, we also assessed the expression of cytotoxic molecules and cytokines, including granzyme B, and tumor necrosis factor-alpha (TNF-α)." (PMID 40799645, 2025). "Meanwhile, the activated CD8+ T cells expressing granzyme B exhibited closer spatial localization with tumor cells that secreted spermidine, indicating that neoplasms with elevated spermidine levels correlate with increased infiltration of GZMB+ CD8+ T cell." (PMID 40959110, 2025).